TNF (tumor necrosis factor)
Diseases named in the same sentence as TNF in open-access papers (continued):
Sharing a sentence is not in itself a finding about the gene and the disease.
malaria (continued). "This augmented production of IL-10 alongside IL-4 heightened levels can directly downregulate key proinflammatory cytokines such as TNF-α, and thus have a protective effect against severe malaria presentations." (PMID 31233500, 2019). "In this study, there was significantly increased production of IL-10 and TNF-α in patients with recurrent malaria." (PMID 34557294, 2019). "Tumor necrosis factor is a major effector cytokine in malaria, with roles in both protection and pathogenesis." (PMID 30239833, 2019). "The differences in TNF-α levels allowed to distinguish the co-infected from both HAT or malaria mono-infected cases, indicating that both diseases synergistically contributed to its elevation." (PMID 31687034, 2019). "Our data show that CD16+ DCs also contribute to TNF production in early infection and potentially during clinical malaria." (PMID 30239833, 2019). "Co-infection led to synergistic stimulation of pro-inflammatory (IFN-γ, TNF-α), and anti-inflammatory (IL-6, and IL-10) cytokine responses relative to malaria mono-infection." (PMID 31687034, 2019). "Secretion of IFN-γ and TNF-α in co-infected cases exhibited a significant positive correlation with each other and was significantly elevated over malaria levels." (PMID 31687034, 2019). "In the blood plasma of malaria patients, an increase in tumor necrosis factor alpha (TNF-α) was found to correlate with the level of extracellular vesicles." (PMID 31878288, 2019). "Severe malaria patients displayed significantly higher plasma TNF-α when compared to uncomplicated P. falciparum infected patients (P = 0.003)." (PMID 31409832, 2019). "Peripheral blood mononuclear cell (PBMC)-derived primary macrophages express increased levels of IL-6, IL-10, IL-1β, and TNF in malaria cases." (PMID 31662766, 2019). "The plasma TNF-α level was significantly elevated in co-infection (52.72 pg/ml) over HAT or malaria mono-infection (P = 0.0438 or P = 0.0134) respectively." (PMID 31687034, 2019). "Elevation of TNF serum levels is a common finding in malaria episodes and was noted that high TNF production capacity correlates with faster parasite clearance and with resolution of malaria attacks." (PMID 31417551, 2019). "While various reports have demonstrated elevated plasma levels of TNF-α in severe malaria compared to uncomplicated infection." (PMID 31409832, 2019). "This was supported by data from pre-clinical malaria models that have shown over-expression of TNF can suppress haematopoiesis in the bone marrow and promote RBC destruction, while IL-10 is thought to enhance hematopoietic activity." (PMID 30809232, 2019). "Nevertheless, TNF serum levels were repeatedly found increased in children with severe malaria implying an intricate role in malaria pathogenesis." (PMID 31417551, 2019). "We show that CD16+ DCs respond to TLR1/2 and TLR4 stimulation with robust TNF production both before and during induced blood-stage malaria." (PMID 30239833, 2019). "A transcriptomic study in Mali described the activation of pro-inflammatory cytokine (IFN-γ, TNF, and IL-1β) production as being influenced by prior exposure to malaria, with asymptomatic infections having the least activation of these cytokines." (PMID 31681289, 2019). "The response of γδ T cells to stimulation in vitro with malaria antigens is characterised by proliferation as well as production of cytokines including IFN-γ, IL-1β, and TNF-α which have been associated with both malaria protection and pathology." (PMID 31600250, 2019). "We observed that two cytokines, TNF and IL‐8, showed a significant correlation with plasma XO activity, suggesting an involvement of this enzyme in malaria‐induced inflammation." (PMID 31265218, 2019). "In severe malaria in Malawian children, the inflammatory monocyte subset was expanded and activated with higher plasma levels of inflammatory cytokines (IFNα, IFNγ, TNF-α, IL-6) and chemokines (CCL2, CCL3, CCL4, CXCL10) than in convalescence." (PMID 30581439, 2018).
malaria (continued). "It is well known that regulation of pro-inflammatory (IFN-γ, TNF-α, IL-6, IL-17) and anti-inflammatory (IL-10, IL-4) cytokines play a pivotal role in malaria parasite growth, protection, and/or pathogenesis." (PMID 29892278, 2018). "When whole blood was stimulated in vitro with LPS, monocytes from children with severe malaria produced less proinflammatory cytokines TNF-α and IL-6 than cells from healthy controls." (PMID 30581439, 2018). "Infected red blood cells and malaria toxins induce immune cells to increase the synthesis of proinflammatory cytokines, such as TNF-α and IFN-γ." (PMID 30515051, 2018). "Several studies have highlighted the role of proinflammatory cytokines as mediators of protective immunity against malaria, including TNF which, together with IFN-γ, acts synergistically to optimise NO production which is important for parasite destruction." (PMID 30199554, 2018). "Approximately a quarter of African children at any one time are infected by malaria and malaria increases hepcidin and tumor necrosis factor-α concentrations leading to poor iron absorption and recycling." (PMID 30275421, 2018). "Patients infected with P. vivax or P. falciparum presented an increase in IFN‐γ, TNF‐α, IL‐6, IL‐8, IL‐10, IL‐13, MIP1β, and G‐CSF levels during the malaria acute phase." (PMID 29314720, 2018). "Studies on human malaria revealed that the cytokine levels of TNFα, IFNγ and IL-12 in PBMCs infected with Plasmodium falciparum in vitro, remained elevated throughout the measurement period of 48 h after infection." (PMID 29495555, 2018). "The release of free hemozoin, presumably from parasites that turn over during the replicative process, coincides with the induction of proinflammatory cytokines, including IL-1β and TNFα, and the periodic fevers characteristic of malaria." (PMID 29495555, 2018). "The main symptom we have considered to define malaria was fever, which is one of the results of some endogenous pyrogen molecules activities, notably pro-inflammatory cytokine TNF-α during the infection." (PMID 30080853, 2018). "For example, an elevated expression of IL-1, IL-6, IL-12, IFN-γ and TNF was found in severe malaria and in hyperparasitemia, a primary clinical feature of severe disease." (PMID 30022038, 2018). "Next, to investigate the profile of the infectious process triggered by P. vivax in patients diagnosed with malaria, patients were divided into two groups using serum TNF-α and IL-4 levels to focus on the serum cytokine profile." (PMID 30126413, 2018). "In the same way, NK and γδT lymphocytes produce IFNγ and TNFα in malaria patients, while polymorphisms within the natural killer cell complex modulate mouse cerebral malaria." (PMID 30533319, 2018). "Using our well-defined prospective cohort, we preliminarily screened six candidate Th1 cytokines (IL-1, IL-6, IL-12, IFN-γ, TNF and TNF-β), and identified IL-12 as a promising molecule for malaria protection." (PMID 30022038, 2018). "PPARγ agonists have been proposed as malaria therapeutics and can increase CD36-mediated phagocytosis of iRBCs while reducing malaria-induced TNFα secretion." (PMID 29891920, 2018). "When administered to mice, GPI induced symptoms that resembled the systemic clinical conditions of malaria, including pyrexia, cachexia, hypoglycemia, and TNF-α-induced sepsis." (PMID 30619355, 2018). "An in vivo study further demonstrated that MCs are a critical source of TNF in addition to Mφ and T cells in murine malaria." (PMID 28428784, 2017). "Similar results were obtained when evaluating the overall percentage of Vδ2+ T cells, and the percentage of Vδ2+ T cells that produced inflammatory cytokines (IFNg, TNF) following in vitro malaria antigen stimulation." (PMID 28904345, 2017). "We observed decreased IL-6 and TNF-α production by monocytes in children with different forms of malaria." (PMID 28122790, 2017).
malaria (continued). "Another study that compared the immune response of patients suffering complicated and uncomplicated malaria caused by P. vivax reported a higher IFN-γ/IL-10 rate in patients having complicated disease, as well as higher TNF-α level." (PMID 28243235, 2017). "TNF-α is the key effector molecule released mainly by activated monocyte/macrophages during malaria." (PMID 28824565, 2017). "During blood-stage malaria, degranulation of Granzyme B, perforin, and exacerbated levels of proinflammatory cytokines such as TNF-α and INF-γ are involved with the damage to the blood–brain barrier." (PMID 28261571, 2017). "We have recently shown that in areas of high malaria transmission, inflammatory CD4 T cells producing IFNγ and TNFα dominate in immune adults, who rarely experience high-density infections or clinical malaria despite constant exposure to infection." (PMID 29097996, 2017). "Malaria-induced antibody production and pathology were unaltered by 11β-HSD1 deficiency though plasma levels of IL-4, IL-6 and TNF-α were slightly affected by 11β-HSD1 deficiency, dependent on the infecting parasite." (PMID 29062028, 2017). "The IL-10-to-TNF-α ratios for all three malaria types (medians, 2.10 for UCM, 2.60 for SMA, and 3.65 for CM) in convalescence were similar to ratios in controls (median, 1.63)." (PMID 28122790, 2017). "There were significant positive correlations between parasite density in children with malaria and levels of key pro-inflammatory cytokines, including TNF-α, IFN-γ and IL-6." (PMID 28399920, 2017). "In conclusion, our data demonstrate that in the context of severe blood‐stage malaria, cDC1 promote the differentiation of parasite‐specific IFNγ+ TNF+ Th1 cells, to the expense of more regulatory IL‐10+ CD4 T cells." (PMID 28935714, 2017). "The response of anti-inflammatory cytokines such as IL-10 and IL-10/TNF-α, IL-10/IFN-γ and IL-10/IL-6 ratios in clinical malaria caused by P. vivax was short-lived and positively correlated with parasitemia rather than with the symptoms." (PMID 28243235, 2017). "Although TNF-α also showed significant higher levels in malaria infected women, many samples were below the TNF-α assay detection limit (127/176 samples with peripheral infection and 238/254 uninfected samples)." (PMID 29255607, 2017). "The majority of triple-positive (81.7%) were IFN-γ+TNF-α+IL2+-expressing at the time of an acute malaria episode." (PMID 29449839, 2017). "The majority of triple-positive [10.5/11.9 (88.2%)] were IFN-γ+TNFα+IL2+-expressing at the time of an acute malaria episode." (PMID 29449839, 2017). "The effects of recombinant TNF in murine malaria parasites has been studied since 1987 and results in vitro and in vivo already showed reduced parasitaemia and prolonged survival in mice infected." (PMID 27080559, 2016). "Since TNF increases cytosolic calcium concentration in P. falciparum and calcium is well known to cross talk with cAMP within several cells including malaria parasites we pre-treated P. falciparum not only with TNF but also with 6-Bnz cAMP." (PMID 27080559, 2016). "The early phase of the immune response to both malaria and bacteremia monoinfections are characterized by the release of greatly elevated levels of cytokines such as TNF-α, IL-1, and IL-6." (PMID 27418744, 2016). "The levels of TNF, IL-6 and IL-10 also increased in the serum of the same three groups during blood stage Malaria." (PMID 27446022, 2016). "TNFα is one of the first recognized pro-inflammatory biomarkers that play important role during malaria." (PMID 27168977, 2016). "Studies have found that TNF-α is elevated in children with severe malaria and increased in children who die of malaria." (PMID 27339303, 2016). "An intricate balance in the host’s eradication of the parasite exists during malaria proliferation through the production of inducible tumour necrosis factor (TNF), oxygen free radicals and other inflammatory mediators." (PMID 27618936, 2016).
malaria (continued). "We conducted this study to explore expression of CD11a, CD11b, CD11c, CD18, HLA‐DR, CD86, TLR‐2 and TLR‐4 and production of TNF‐α and IL‐6 by monocytes in Malawian children presenting with different clinical forms of malaria." (PMID 27027867, 2016). "IFN-γ, TNF-α, IL-6, IL-12, IL-1β, and IL-8 are reported at higher levels in individuals infected with Plasmodium than in controls or in individuals with severe malaria." (PMID 27999453, 2016). "Participants with DDX39B-22/DDX39B-348/TNF-308/IL6-176 genotype combinations GC/CC/GG/GG and GG/CT/GG/GG had reduced and increased risk, respectively, of developing malaria symptoms." (PMID 26858717, 2016). "Proinflammatory cytokines, such as IFN-γ and TNF, are involved in the resolution of malaria and are required for protection." (PMID 27245410, 2016). "The data presented here demonstrate that high levels of the circulatory pro‐inflammatory, TNF‐α, and IL‐6, are indicators of malaria severity, whereas anti‐inflammatory cytokine IL‐10 level does not differentiate SM and MM cases." (PMID 27042299, 2016). "After adjustment for age, plasma TNF-α levels correlated positively with sEPCR levels in children with severe malaria (β-coefficient 0.03, 95% CI 0.002–0.06, P = 0.04)." (PMID 27255786, 2016). "During acute malaria, percentages of TNF‐α‐ and IL‐6‐producing monocytes in all clinical groups were significantly lower than in controls, with children with CM having the lowest percentage." (PMID 27027867, 2016). "The data analysis demonstrated that both malaria groups have significantly increased levels of IL-2, IL-4, IL-6, IL-10, TNF and IFN-γ as compared to the endemic controls." (PMID 27581163, 2016). "In malaria infection, TNF- is produced by monocytes / macrophages exposed to malaria parasites, the soluble antigens (such as glycosylphosphatidylinositol (GPI)) and malaria pigment (hemozoin)." (PMID 27222837, 2016). "Pro‐inflammatory cytokines, such as TNF‐α and IL‐6 which are produced by monocytes among other cells, are elevated in severe malaria and appear to be important for controlling infection." (PMID 27027867, 2016). "Little is known about ADAM17 in malaria, but the cleavage of host receptors specifically utilized by IEs in severe malaria patients and cytokines, such as TNFα, which are increased in SM, suggests ADAM17 plays a role in malaria pathogenesis." (PMID 27784899, 2016). "A further placebo controlled trial conducted in 28 Thai adults >14 years old (enrolled using WHO severe malaria criteria) investigated polyclonal anti-TNF-α antibodies in addition to artesunate." (PMID 25858094, 2015). "Both NK cells and γδ T cells have been implicated in the production of proinflammatory cytokines gamma interferon (IFN-γ) and tumor necrosis factor alpha (TNF-α) in malaria (27, –, 29)." (PMID 26581890, 2015). "The presence of TNF as a trigger of inflammation in malaria led to the assessment of a TNF-blocking approach in CM." (PMID 26259939, 2015). "Heightened levels of TNF and IFN-γ have been systematically associated with increased clinical disease severity in malaria or dengue fever in many case series." (PMID 26271921, 2015). "Network analyses of plasma cytokines/chemokines revealed that malaria and dengue co-infection exhibits a distinct immune profile with critical roles for TNF, IL-6 and IFN-γ." (PMID 26271921, 2015). "The transcriptional profile following treatment of erythroblasts with either TNF-α or hemozoin shares some overlap with previous observations in peripheral blood of children with acute malaria and in murine models of malaria." (PMID 25781011, 2015). "IL-6 and TNF-α belong to the innate cytokines, they play important roles in the pathogenesis of malaria." (PMID 25889652, 2015). "IFN-γ and TNF showed the highest relative number of network interactions in the severe malaria group and IL-1β and IL-6 showed the highest relative number of interactions in the hyperbilirubinaemia group." (PMID 26466783, 2015).
malaria (continued). "TNF exhibited the highest number of interactions in the group of patients with malaria and dengue co-infection." (PMID 26271921, 2015). "PLA2 activity is tightly regulated by host responses including TNFα and reactive oxygen species (ROS), both of which can be elevated during severe malaria." (PMID 26691993, 2015). "Polyfunctional T cells co-producing IFN-γ, TNF-α and IL-2 are associated with infection control in HIV, hepatitis C, leishmaniasis and malaria." (PMID 25879774, 2015). "Remarkably, the role of TNFα and other pro-inflammatory cytokines in parasitic infections, including P. falciparum, is ambiguous: TNFα has been identified to promote parasite killing, but it also contributes to development of severe malaria disease." (PMID 25759693, 2015). "The expression of TLR4 by these populations makes them susceptible to the inflammatory effects of deleterious TLR4 activators TNFα and IFNγ, both of which are up-regulated in malaria." (PMID 26555697, 2015). "Severe malaria is characterized by elevated levels of the inflammatory cytokine TNF-α which is thought to be produced following phagocytosis of malarial pigment (hemozoin) by macrophages." (PMID 25781011, 2015). "The pathogenesis of severe malaria involves several different processes, including enhanced production of the cytokines including tumour necrosis factor (TNF), sequestration of parasite red cells to the endothelium and decreased erythrocyte deformability." (PMID 25858094, 2015). "Awareness of the capacity of excess TNF to cause disease arose from parallels between our work on BCG, LPS, and malaria and earlier work of the discoverers of TNF, who worked in a tumor context." (PMID 26221543, 2015). "TNF is a known mediator of anorexia and cachexia seen in many human disease states and is elevated during acute malaria." (PMID 26377094, 2015). "Network analyses revealed that cases of malaria and dengue co-infection exhibit a unique immune profile with a special role for TNF, IL-6, IFN-γ, and IL-7." (PMID 26271921, 2015). "Overall, malaria and dengue co-infection displayed lower levels of platelets and haemoglobin and a specific immune signature with a special role for TNF compared to dengue or malaria." (PMID 26271921, 2015). "On the other hand, malaria patients produced lower levels of TNF-α, IL-12p70, and IL-2 than healthy individuals." (PMID 24741587, 2014). "Such a potentiating effect has been described for TNF, a cytokine whose plasma levels are elevated in severe malaria." (PMID 24686750, 2014). "Course and outcome of both human and experimental blood-stage malaria critically depend on a finely tuned balance between both pro-inflammatory cytokines, as, e.g., IL-1β, TNFα, IFNγ, IL-6, and IL-12, and anti-inflammatory cytokines such as IL-4 and IL-10." (PMID 25408684, 2014). "TNF is an important cytokine in malaria within pregnancy and its levels must be carefully regulated." (PMID 25124540, 2014). "Produced only by lymphocytes, LT and TNF are thought to work synergistically to induce hypoglycaemia and increased serum levels of interleukin-6 in severe malaria." (PMID 26430675, 2014). "The use of principal component analysis and cluster analysis associated increased levels of IL-6, TNF-α, IL-10, and CRP and low levels of IL-17A predominantly with individuals with malaria alone and coinfected individuals." (PMID 25309052, 2014). "It was shown that PD-1 mediated a reduction in the capacity of parasite-specific CD4+ T cells to proliferate and secrete IFN-γ and TNF-α during the chronic phase of malaria (day 35) indicating exhaustion of these cells." (PMID 24904561, 2014). "Taken together, the allele frequency of TNF-836 C and IFN-γ-1616 T genes were statistically significantly higher in those with severe malaria infection compared to uncomplicated malaria patients." (PMID 25124540, 2014).